CD4 (CD4 molecule)
Diseases named in the same sentence as CD4 in open-access papers (continued):
Sharing a sentence is not in itself a finding about the gene and the disease.
ovarian carcinoma (continued). "We found that the ovarian cancer cells that expressed PD-L1 proteins on their membrane also expressed very high expressions of CD8 and moderate expressions of CD4 in all ovarian cancer histological types." (PMID 36604635, 2023). "The proportion and phenotypic characteristics of CD4+CCR8+ Tregs in peripheral blood of healthy individuals, peripheral blood of OC patients and OC tissues were clarified as well as the effect of ovarian cancer microenvironment on CD4+CCR8+ Tregs recruitment." (PMID 37950246, 2023). "In mouse models of ovarian cancer, co-blocking LAG3 and PD-1 expressed on CD4 + and CD8 + TILs induces enhanced anti-tumor response." (PMID 38115039, 2023). "In contrast to CD4+ and CD8+ TILs, CD45+ tumor-infiltrating leukocytes in ovarian cancer are a somewhat less researched area, and in many cases, the naive (CD45RA) and the memory (CD45RO) T cell isoforms are specifically investigated." (PMID 37761986, 2023). "In contrast, it was reported that infiltration of CXCL13-producing CD4+ T cells precedes HEV and TLS formation in the ovarian cancer microenvironment." (PMID 37476074, 2023). "In contrast, a study reported that there is a negative correlation between the regulatory T cell activity of CD4+ and CD25+ and the outcome of ovarian cancer patients and that CD4+CD25+FOXP3+Treg cells tend to accumulate primarily in tumors or ascites." (PMID 36674491, 2023). "The levels of lymphocyte infiltration were assessed in the ovarian cancer tissues by staining the cancer sections with antibodies against lymphocyte markers CD8 and CD4." (PMID 36604635, 2023). "Pseudotime analysis showed that the transition of Th1 cells into CD4+ Tpex and CD4+ Ttex in mice with LLC or ovarian cancer was a dynamic process similar to that of CD8+ T cells, suggesting that RACIM can effectively reverse this transition." (PMID 37208386, 2023). "Labeling sections for CD4+ and CD8+ T cells showed that huPDX3 TILs were primarily CD4+ (CD4+/CD8 average ratio of 4.7 ± 3.3), which correlates with poor survival in patients with ovarian cancer." (PMID 36860657, 2023). "As for ovarian cancer, previous studies proposed that TLS coordinates the infiltration of T cells, such as the cytotoxic T cell and CXCL13-producing CD4+ T cells, and antibody-producing PCs to advance antitumor responses." (PMID 36704336, 2022). "P-gp-expressing CD4+T cells (CD4+CD73+T cells) were found to secrete more anti-cancer cytokines in tumour-infiltrating breast and ovarian carcinomas." (PMID 35743927, 2022). "To investigate which factors promote CXCL13 secretion from CD4+ T cells and CD8+ T cells, we analyzed 2 sets of gene expression data from ovarian cancer tissues." (PMID 35552285, 2022). "We showed that, in ovarian carcinoma, CD8+ T cells were dominant among TILs, whereas CD4+ cells were dominant in the TLS." (PMID 35552285, 2022). "TALs from ovarian cancer patients confirmed the upregulation of LAG-3 and PD-1 on both CD8+ and CD4+ T cells." (PMID 36359346, 2022). "In the B16‐OVA syngeneic mouse model and ovarian cancer, oncolytic adenoviruses increased the proportion of tumor‐infiltrating CD8+ T cells and CD4+ T cells, leading to significant reduction in tumor growth." (PMID 35762456, 2022). "To elucidate which specific immune cell population was responsible for our antitumor efficacy results, we used antibodies against CD4+ T cells, CD8+ T cells, or CD20+ B cells in ovarian cancer–bearing mice treated with RPE-mIL2." (PMID 35235346, 2022). "The CTA NY-ESO-1, a homologous family member of TMEFF1, can induce a higher antibody titer and CD4+/CD8+ T cell immune response, with a vaccine treatment prolonging the progression-free survival of patients with advanced ovarian cancer." (PMID 34475991, 2021).
ovarian carcinoma (continued). "HAVCR2 is significantly overexpressed in CD4+and CD8+T cells and suppress the antitumor immune responses in primary ovarian cancer, the blockade of HAVCR2 leads to sustained antitumor reactions." (PMID 34484333, 2021). "Early studies by Sato and colleagues evaluated the high levels of intraepithelial CD8+ TILs and CD4+/CD25+ Treg cells in the epithelium and stroma of several histologic subtypes of ovarian cancer (OvCa)." (PMID 33467127, 2021). "In a study of leukocytes from peripheral blood mononuclear cells, the level of TIM-3 expression was significantly higher in the CD4+ and CD8+ T cells of ovarian cancer patients." (PMID 34940257, 2021). "We also observed a weak, but statistically significant correlation between T CD4+TLR2+ lymphocytes and HE4 serum concentration, which is a biomarker for ovarian cancer and until now was understood as a hormone-dependent factor." (PMID 32751735, 2020). "The immunoreactivity of DC vaccines in ovarian cancer is mainly described by the alteration of the following immune cells: CD8+T cells, CD4+T cells, Tregs and NK cells." (PMID 33584699, 2020). "The expression of resting memory CD4 T cells, M2 macrophages, and neutrophils was positively correlated with the status of signatures combined with TMB expression in ovarian cancer patients." (PMID 33381581, 2020). "In summary, our study demonstrated the feasibility of efficiently identifying both CD4+ and CD8+ neoantigen-specific T-cells in ovarian cancer." (PMID 31221207, 2019). "It is reported that XBP1 KO CD11b+ DCs infiltrating ovarian cancer tumors are more efficient to activate anti-tumor CD8+ and CD4+ T cell responses and can control tumor growth." (PMID 30687308, 2018). "Although IL-17 is secreted by CD4+ T cells and CD68+ macrophages in ovarian cancer, in other types of cancer, a population of FoxP3+ regulatory T cells (Treg), that under certain conditions express IL-17, plays a critical role in the regulation of CSCs." (PMID 28819364, 2017). "The results of the present study show for the first time positive relationship between triple stained CD4+CD25highFoxP3+ cells and concentration of CCL22 chemokine in the peritoneal fluid of patients with ovarian cancer." (PMID 25647263, 2015). "We also studied relationships between the percentage of regulatory CD4 + CD25 + FOXP3+ T lymphocytes and TGF-beta concentration in the microenvironment of benign and malignant ovarian tumors in comparison with the reference group." (PMID 26077607, 2015). "In ovarian cancer, hypoxia-induced angiogenesis, human, and mouse CD4+CD25+ Tregs secrete higher amounts of VEGFA (as compared to CD4+CD25− T cells) and promote EC proliferation in vitro and in vivo." (PMID 25072019, 2014). "CCL5 produced by CD4+ T cells activated CC5R+ dendritic cells, eliciting tumor-reactive CD8+ T cell to kill ovarian cancer cells through CD40." (PMID 24213462, 2012). "We found that aAPCs efficiently expand IL-2 cultured TILs from solid tumor specimens of ovarian cancer similar to the REM, resulting in a favorable CD4/8 T cell ratio, and low FOXP3+ CD4 T cell composition." (PMID 21827675, 2011). "In contrast, the presence of the CD4-positive regulatory subtype of T lymphocytes (Treg; CD4+CD25+FoxP3+) seems to reduce tumour-specific immunity and results in poorer survival of patients with ovarian carcinomas." (PMID 19861998, 2009). "Formalin-fixed and paraffin-embedded ovarian carcinomas were examined for CD20-, CD3-, CD4- and CD8-positive lymphocytes (n=100), and for Her2/neu-positive tumour cells (n=55/100) by immunohistochemistry." (PMID 19861998, 2009). "The frequency of immune cells, including B cells, CD4+ cells, CD8+ cells, macrophages, and plasma cells, was significantly increased in ovarian cancer patients, and the frequency of other cell types, such as endothelial cells, NK cells, and pericytes/SMCs, was decreased." (PMID 40196737, 2025).
ovarian carcinoma (continued). "However, Kroeger and colleagues reported that the prognostic benefit of CD8(+) TILs in patients with ovarian cancer was limited and was only achieved in the presence of PCs, CD20+ TILs and CD4+ TILs." (PMID 39569184, 2024). "MS4A1 expression is positively correlated with CD4+ and CD8+T cell infiltration in ovarian cancer." (PMID 37762518, 2023). "First, we did not directly prove that CXCL13 secreted from CD4+ T cells induced TLS in the mouse ovarian cancer model." (PMID 35552285, 2022). "In addition, histological analysis of ovarian cancer tumor tissue pre- and post-neoadjuvant chemotherapy (NACT) has shown that chemotherapy can upregulate TILs including CD8, CD4, and CD20 infiltration." (PMID 36428740, 2022). "Olalekan has revealed that ovarian cancer with high infiltration of CD8+ TOX+ and CD4+ GNLY T cells may be a good indication for patients." (PMID 35935940, 2022). "However, low expression of PD-L1 significantly increased the expression of CD4 + T cells, CD8 + T cells, NK cells and CD11C + M1 macrophages in ovarian cancer, whereas significantly inhibited the expression of regulatory T cells." (PMID 36311731, 2022). "Among them, activated CD4 and activated CD8 were only two types of immune cells that could promote the ovarian cancer progress in the ferroptosis-related pathway, and similar results were also reported in the previous studies." (PMID 35039008, 2022). "We also observed that the CXCL13-producing CD4 + T cells could facilitate the formation of TLS and strengthen the cooperative antitumor activity of cellular and humoral immunity in ovarian cancer." (PMID 36704336, 2022). "Thus, we investigated the impact of conditioned media of ovarian cancer cells subjected to PDT on PBMC by studying the activation status of various T lymphocyte populations, including CD4 + and CD8 + T cells." (PMID 32326210, 2020). "Interestingly, the tumor infiltrating P-gp-expressing CD4+T-cells (CD4+CD73+T cells) in breast and ovarian carcinomas were shown to exert enhanced secretion of these anti-cancer cytokines." (PMID 32195185, 2020). "Accordingly, in an ovarian carcinoma-bearing mice model, IFN-γ-stimulated M-MDSC increased MHC class II, CD80, and IL-10 expression, and induced CD4+CD25+ Treg in a CTLA-4/CD80-dependent manner, which is in line with our results on IL-10-producing GM-CSF/IL-6 M-MDSC." (PMID 30936876, 2019). "The correlations between the individual gene expression of the LMGS and the abundance of immune infiltrates, including B cells, CD4+ T cells, CD8+ T cells, neutrophils, macrophages, and dendritic cells, were all significant but extensively weak in ovarian cancer samples." (PMID 31888563, 2019). "For example, Hospicells expressing the cell surface markers CD9, CD10, CD29, CD146, and CD16 in stroma produce a large amount of nitrous oxide (NO), which suppresses CD4(+), CD8(+) and Vγ9Vδ2 T cell proliferation and cytokine production, eventually conferring chemoresistance on ovarian cancer cells." (PMID 28929459, 2018). "CD4+IL-17A+ TALs restimulated in ovarian cancer conditioned medium, but not in the presence of Th17-driving cytokines or TGFβ, demonstrate increased production of IL-10." (PMID 28290453, 2017). "In line with a role for Th17 cells in the recruitment of immune cells within tumors, Th17 cells in human ovarian cancers were positively correlated with IFN-γ+ CD4+ T cells, IFN-γ+ IL-17+ CD4+ T cells, and IFN-γ+ CD8+ T cells, whereas negatively correlating with Treg cells." (PMID 26583099, 2015). "In our studies the percentage of Treg lymphocytes among CD4+ T lymphocytes was assessed in two compartments: in peripheral blood and in the microenvironment of the neoplastic tissue of non-malignant and malignant ovarian tumors." (PMID 26077607, 2015). "Compared with the corresponding nontumor tissues, the levels of Tim-3-expressing CD4 T cells were also significantly higher in tumors from patients with colorectal, cervical or ovarian carcinoma." (PMID 23526963, 2013).
ovarian carcinoma (continued). "They found that CD3+CD4+ T cell populations and CD14+ macrophages in the ascites preferentially express CCR2 and CC5R, suggesting that they play important roles in CC chemokine networks of ovarian cancer ascites." (PMID 24213462, 2012). "In ovarian carcinomas, stromal CD20-, CD3-, CD4- and CD8-positive lymphocytes were detected in 57.7, 99.0, 96.4 and 91.7% of cases and intraepithelial CD20-, CD3-, CD4- and CD8-positive lymphocytes were detected in 33.0, 90.2, 74.4 and 81.4% of cases, respectively." (PMID 19861998, 2009). "In contrast, the presence of the CD4-positive regulatory subtype of T lymphocytes (Treg; CD4+CD25+FoxP3+) seems to reduce tumour-specific immunity and results in a poorer survival of patients with ovarian carcinomas." (PMID 19861998, 2009). "In addition, chemokine-mediated recruitment of CD4+CD25+ T regulatory cells to the tumour bed, has recently been described in ovarial cancer." (PMID 16641897, 2006). "The results showed that TIPE2 expression correlated positively with the tumor-infiltrating immune cells in ovarian cancer, including CD8+ T cells, CD4+ T cells, Treg cells, activated DCs, NK cells, macrophages, mast cells, and Tfh, suggesting that TIPE2 may impair the TME of ovarian cancer." (PMID 36801818, 2023). "The decrease in CD4, associated with a tendency towards an increase in CD8, led to a dramatic decrease in the CD4 to CD8 ratio, a result consistent with previous work demonstrating it represented a favorable prognosis marker for overall survival in vaccine-treated ovarian cancer patients." (PMID 36430209, 2022). "In addition, as seen in ovarian cancer, there was also a clear link between the expression of IFNG, CXCL13, CD30, and PRF1 and presence of immune cells within the tumor, including B cells, CD8+ T cells, CD4+ T cells, dendritic cells, and neutrophils." (PMID 31998644, 2019). "The main focus of our study was to examine the association of tumor infiltrating CD4+CD25+FOXP3+ Tregs and other T cells with clinical outcome in epithelial ovarian cancer patients, since this approach of triple staining has not been done in ovarian tumors to the best of our knowledge." (PMID 24244610, 2013). "However, the CD4+CD25+FoxP3+ Tregs suppress tumor-specific T-cell immunity and increased Tregs in the tumor micro-environment can be related to the disease severity and poor outcome of ovarian carcinoma." (PMID 23082146, 2012). "We found that CD4+ T cells could independently delay tumor progression but a mixed population of CD4+ and CD8+ T cells induced greater antitumor efficacy against our aggressive model of ovarian cancer." (PMID 21076522, 2010). "In vivo models studying olaparib in BRCA1-deficient ovarian cancer observed significantly increased proportions of CD4+ and CD8+ effector T-cells infiltrating intratumorally and peripherally and, notably, an increase in intra-tumoral CD4/Foxp3+ Tregs was not seen." (PMID 36159999, 2022). "Interestingly, TGF-β, but not ovarian cancer conditioned medium, also promotes Il17a expression in CD4+IL-17A+ TALs, suggesting that TGFβ might be promoting IL-17A+Foxp3+ cells while the tumour microenvironment promotes exTh17 Foxp3+ T cells." (PMID 28290453, 2017). "Indeed, some studies have shown that FOXP3 expression is elicited in activated T cells with no regulatory activities, which could lead one to speculate that some of the CD4+CD25+FOXP3+ T cells in ovarian cancer may not be regulatory." (PMID 24244610, 2013). "In ovarian cancer, one study examined the prognostic significance of NLR and CD4+ and CD8+ TILs in HGSC cases but did not assess the relationship between NLR and TILs." (PMID 41463155, 2025).
ovarian carcinoma (continued). "Similar results were observed in samples isolated from human patients with colorectal, cervical and ovarian carcinoma, including the selective impairment of IFN-γ and IL-2 production in Tim-3+ CD4 T cells isolated from TILs (data not shown)." (PMID 23526963, 2013). "Unlike in ovarian cancer, we found that the expression level of CD30 correlated with the infiltration level of B-cells (part.cor = 0.476), CD8+ T cells (part.cor = 0.25), CD4+ T cells (part.cor = 0.33), neutrophils (part.cor = 0.299), and dendritic cells (part.cor = 0.449)." (PMID 31998644, 2019).